EGFR (epidermal growth factor receptor)
Diseases named in the same sentence as EGFR in open-access papers (continued):
Sharing a sentence is not in itself a finding about the gene and the disease.
chordoma (continued). "Several chordoma dependency genes identified in the primary screens, including PTPN11, EGFR, and CDK6, encode proteins that are currently targetable with small-molecule inhibitors." (PMID 37024492, 2023). "Immunostaining for PDGFRα, EGFR, and c-MET in the chordoma patients’ samples showed an increase in these three proteins and prompted multiple investigations to target EGFR." (PMID 37111759, 2023). "Targeting PTEN, EGFR, C-Mte, and PD-1 can provide potential strategies for the treatment of chordoma." (PMID 36520826, 2022). "Epidermal growth factor receptor (EGFR) is highly expressed in 40% of chordomas, and targeting EGFR has been shown to be both effective in chordoma cell lines and murine xenograft models." (PMID 35896603, 2022). "For instance, in patients with PDGFRβ‐positive chordomas, the first and second‐line therapies are tyrosine‐kinase (imatinib) and epidermal growth factor receptor (EGFR) inhibitors (erlotinib), respectively." (PMID 36258855, 2022). "Several quinazoline-based clinical kinase inhibitors whose main target is EGFR have been shown to inhibit chordoma cell lines, including gefitinib, erlotinib, afatinib and lapatinib 4,8–12." (PMID 35896603, 2022). "While exploring cyclin G associated kinase (GAK) as a potential collateral target to treat chordoma, we identified a series of potent EGFR inhibitor starting points based on the 4-anilinoquinazoline scaffold, exemplified by 110,12." (PMID 35896603, 2022). "This screening and optimization effort has produced a series of useful tools for further interrogation of EGFR biology, and more specifically, chordoma inhibitor development." (PMID 35896603, 2022). "Inhibitors of wild-type EGFR, such as afatinib and cetuximab, have reproducibly shown promising activity against chordoma cell lines and xenograft models, which has motivated two Phase II clinical trials (NCT03083678 and NCT05041127)." (PMID 36387127, 2022). "As one of the most well-validated therapeutic targets in chordoma, inhibitors of wild-type EGFR are arguably the best ‘anchors’ to initially explore in unbiased screens or rational combination studies." (PMID 36387127, 2022). "There have been a number of clinical trials that have evaluated EGFR inhibitors to treat chordomas, but treatment outcomes are highly variable, and molecular mechanisms underlying this observed variability are not well understood." (PMID 35896603, 2022). "Increased EGFR inhibition generally increased the efficiency of inhibition on the chordoma cell lines." (PMID 35896603, 2022). "The two lead compounds 41 and 45 are potent narrow spectrum EGFR inhibitors that provide exciting starting points for further optimization towards a potenital clinical compound to combat chordoma." (PMID 35896603, 2022). "Early clinical outcomes of agents targeting PDGFR, EGFR, c-Met and other elements of the chordoma molecular pathophysiological cascade have been modest but our understanding continues to evolve." (PMID 33806339, 2021). "CMTM3 suppressed the migration and invasion of chordoma cells through the EGFR/STAT3/EMT signaling pathway." (PMID 34560882, 2021). "Previous work by our group has also demonstrated that an anti-EGFR mAb, cetuximab, mediates NK-cell lysis of chordoma cells via ADCC." (PMID 35765577, 2021). "Taken together, CMTM3 suppresses chordomas metastasis via accelerating EGFR degradation and suppressing the EGFR/STAT3/EMT signaling pathway." (PMID 34560882, 2021). "Our previous study also found that EGFR played important roles in chordoma tumorigenesis and development." (PMID 34560882, 2021). "Flow cytometric analysis of 6 chordoma cell lines revealed higher EGFR expression than PD-L1 expression." (PMID 35765577, 2021).
chordoma (continued). "To date, the clinical relevance of EGFR in chordoma development is still controversial because of its relatively low incidence rate." (PMID 34560882, 2021). "Adle-Biassette demonstrated that EGFR was expressed in 244/284 (85.9%) of chordomas and Yilmaz found that intensely positive EGFR was revealed in 77.5% (38/49) of chordoma patients." (PMID 34560882, 2021). "Further integrated analysis of both the miRNA-mRNA and PPI networks data identified an important regulatory role for miR-574-3p-mediated signaling pathways in chordoma, especially the EGFR pathway." (PMID 33194623, 2020). "Taken together, these outcomes further highlight the clinical significance of immune microenvironment in chordoma and suggest a complete miR-574-3p/EGFR/Ras/Mek/PD-L1 signaling network involved in chordoma development." (PMID 33194623, 2020). "Bioinformatical analysis revealed an important regulatory role for miR-574-3p/EGFR signaling in chordoma and showed that the target genes of these prognostic miRNAs were mainly enriched in transcription regulation, protein binding and cancer-related pathways." (PMID 33194623, 2020). "There is preclinical evidence of the role of epidermal growth factor receptor (EGFR) in chordoma pathogenesis and also a few case reports elucidating the role of blocking this receptor leading to meaningful clinical responses." (PMID 33308288, 2020). "Afatinib was also found to promote degradation of EGFR and brachyury, both of which are crucial to chordoma cell growth." (PMID 32737414, 2020). "For PDGFR-positive and/or EGFR-positive chordoma, clinical benefits were achieved with acceptable AEs." (PMID 30775316, 2019). "HER2/neu is involved in EGFR dimer formation, and the possibility of heterodimerization increases the sensitivity of EGFR-positive chordoma to 54%." (PMID 30775316, 2019). "The anti-EGFR monoclonal antibody (mAb) cetuximab was applied in combination with erlotinib in one patient with EGFR-positive chordoma, and he had a SD for 6 months." (PMID 30775316, 2019). "Erlotinib was the most commonly used anti-EGFR agent and was analyzed in 10 studies (16 patients) for the treatment of chordoma, including one clinical trials, one retrospective case study and eight case reports." (PMID 30775316, 2019). "Combined regimen of cetuximab and gefitinib was also effective in two cases of EGFR-positive chordoma, where one achieved a PR for 9 months and the other had a 44% reduction in tumor bulk." (PMID 30775316, 2019). "Molecular targeted therapy of chordomas with EGFR inhibitors (erlotinib, linsitinib, cetuximab, lapatinib, gefitinib)." (PMID 30775316, 2019). "Compared with controls, the HRASV12-, EGFR- and kdr-overexpressing notochords also stained notably stronger for the common chordoma marker pan-Cytokeratin." (PMID 31221659, 2019). "Lapatinib monotherapy was evaluated in a phase II clinical trial on 18 patients with EGFR-positive chordoma." (PMID 30775316, 2019). "standard therapy in different setting is warranted, considering the high rate of EGFR- positive chordomas and preclinical encouraging data." (PMID 28775967, 2017). "We describe the case of a 69-year old male with an EGFR- positive Imatinib refractory sacral chordoma with synchronous lung metastases, treated with erlotinib, a first-generation EGFR inhibitor." (PMID 28775967, 2017). "EGFR inhibitors in clinical development were then studied on an extended cell line panel of seven chordoma cell lines, four of which were sensitive to EGFR inhibition." (PMID 27102572, 2016). "We propose that such a study should involve in‐depth biological studies of the tumour samples pre‐ and post‐treatment, with the aim of explaining the mechanism by which some chordomas are primarily resistant or develop secondary resistance to EGFR inhibitors." (PMID 27102572, 2016).
chordoma (continued). "We suggest that trials incorporating assessment of these parameters should evaluate the effects of combined IGF-1R/INSR and EGFR inhibition in patients with recurrent chordomas." (PMID 27200287, 2016). "The collective data from this study show that EGFR inhibitors represent the group of compounds within our extensive screen that were most effective against chordoma cell growth." (PMID 27102572, 2016). "Similar to these tumours, chordoma cell lines express the activated form of the receptor and show suppression of the downstream EGFR signalling pathways following treatment with EGFR inhibitors." (PMID 27102572, 2016). "Previous studies implicated receptor tyrosine kinases, including epidermal growth factor receptor (EGFR) and type 1 insulin-like growth factor receptor (IGF-1R), in chordoma biology." (PMID 27200287, 2016). "EGFR expression has been detected by IHC in ~70% of chordomas, with high level EGFR copy number gain in 40%, and suppression of in vitro chordoma cell growth by a tyrphostin EGFR inhibitor." (PMID 27200287, 2016). "Numerous tyrosine kinase receptors are richly expressed in chordoma cells, such as EGFR (epithelial growth factor), α and β PDGFR (platelet-derived growth factor), c-KIT and IGF-1 receptor." (PMID 26391590, 2015). "Inhibitors of the mTOR pathway (sirolimus) and inhibitors of EGFR (cetuximab/gefitinib) have also been used in cases of resistant chordomas or metastatic chordoma of the sacrum." (PMID 26391590, 2015). "Our study shows that such combined targeting of Bcl-xL and EGFR can be achieved by overexpression of miR-608, providing a novel and powerful rationale for the therapeutic restoration of this microRNA in chordoma therapy." (PMID 24621885, 2014). "We therefore identified and characterized miR-608 and miR-34a as novel tumor suppressive miRNAs in chordoma that directly target EGFR, Bcl-xL or MET." (PMID 24621885, 2014). "We analyzed the correlation of miR-608 and EGFR expressions in chordoma cells and found that miR-608 level is inversely correlated with EGFR protein levels (R2 = 0.8, P<0.05)." (PMID 24621885, 2014). "We find that miR-34a inversely correlates with MET expression and miR-608 inversely correlates with EGFR expression in chordoma cells." (PMID 24621885, 2014). "In fact, studies have found that 27–40% of chordomas have amplified EGFR and 27–50% have amlplified MET genes." (PMID 24621885, 2014). "The epidermal growth factor receptor (EGFR) antagonists have also been shown to be effective in patients with chordoma refractory to imatinib." (PMID 25018886, 2014). "A few studies have shown that EGFR is one of the most frequently activated RTKs in chordomas and that its activation correlates with aggressive tumor behavior." (PMID 24621885, 2014). "Our study uncovers for the first time miR-608 downregulation as a new mechanism of EGFR overexpression in chordoma." (PMID 24621885, 2014). "We measured miR-608 levels by qRT-PCR and EGFR protein levels by immunoblotting in chordoma cell lines, primary cells and normal fibroblasts." (PMID 24621885, 2014). "Though EGFR activation has frequently been observed in chordomas, EGFR inhibitors have rarely been used clinically in this disease." (PMID 24260133, 2013). "Given activation of the EGFR pathway in the chordoma PDX, we next evaluated the efficacy of small molecule EGFR inhibitors against a validated chordoma cell line U-CH 1, which has also been shown to have activated EGFR." (PMID 24260133, 2013). "Activation of EGFR has also been investigated in several studies; these studies reported between 43 and 100% of chordomas express phosphorylated EGFR." (PMID 24260133, 2013). "To ascertain the effect of EGFR inhibition in vivo, we examined the efficacy of erlotinib in our chordoma PDX." (PMID 24260133, 2013). "This is the first demonstration of antitumor activity in a patient-derived chordoma xenograft model and these findings support further evaluation of EGFR inhibitors in this disease." (PMID 24260133, 2013).
chordoma (continued). "Our array analysis demonstrated that EGFR is significantly activated in the chordoma PDX, consistent with other recent reports on chordoma samples." (PMID 24260133, 2013). "These immunohistochemistry-based studies reported that between 32 and 100% of the chordoma samples examined were positive for EGFR." (PMID 24260133, 2013). "In the largest study evaluating EGFR in chordoma, EGFR expression was reported in 79 out of 114 (69%) chordomas and 57 out of 115 (51%) samples expressed phosphorylated EGFR." (PMID 24260133, 2013). "Here, we report on a patient with EGFR-overexpressing advanced chordoma that progressed on imatinib and subsequently responded to erlotinib." (PMID 21970335, 2011). "Three cases of advanced chordoma benefiting from EGFR inhibitors have been reported to date in the literature: two were treated with the gefitinib-cetuximab combination, and one with erlotinib alone." (PMID 21970335, 2011). "The activation of EGFR in chordoma was previously shown by other groups, although the reported frequencies of the EGFR activation in chordoma vary significantly." (PMID 22613809, 2011). "The targeting of EGFR represents an attractive challenge in chordoma, which clearly calls for prospective assessment in multicentric clinical trials." (PMID 21970335, 2011). "Of the 39 chordomas tested by IHC for EGFR expression, 19 were primary and 20 were advanced lesions." (PMID 22613809, 2011). "Our case highlights the antitumor activity of EGFR inhibition in advanced chordoma, in agreement with three other clinical cases previously reported and pre-clinical data." (PMID 21970335, 2011). "Other groups found EGFR activation in three out of three and in about 50% of chordomas evaluated by RTK antibody arrays and immunohistochemistry respectively." (PMID 22613809, 2011). "Recent reports describing antitumor activity of EGFR inhibitors in chordoma led us to analyze tumor samples collected from relapses excised in July 2007 and February 2008." (PMID 21970335, 2011). "We report on a 76-year-old patient with EGFR-overexpressing advanced chordoma that progressed on imatinib and subsequently responded to erlotinib during 12 months." (PMID 21970335, 2011). "Again in contrast to Weinberger and co-workers, we did find a positive correlation between HER2 expression and EGFR expression, which is in line with the HER2/EGFR heterodimers formation in chordomas reported by other groups." (PMID 22613809, 2011). "Simultaneous expression of c-Met and EGFR has been observed in clinical specimens of primary chordoma and gastrinoma." (PMID 21673683, 2011). "EGFR, a receptor tyrosine kinase involved in cellular proliferation, survival, and differentiation, is frequently found to be overexpressed or phosphorylated in chordoma samples, especially those from the sacral and skull base regions." (PMID 40943706, 2025). "EGFR targeted therapies utilized in advanced chordoma include lapitinib and erlotinib." (PMID 38881706, 2024). "EGFR expression on chordoma cells is well described in the literature." (PMID 39696530, 2024). "Moreover, YBX1 enhanced EGFR transcription by directly binding to its promoter in chordoma cells, thereby regulating protein expression of p-EGFR, p-AKT and its downstream target genes that influence cell apoptosis and cell cycle transition." (PMID 38255791, 2024). "Genes marked on the volcano plot were either implicated earlier in chordoma biology (e.g. keratins—KRT8, KRT18, KRT19, TBXT, LMX1A, and EGFR) or identified by outstanding p-value (e.g. IL11, CD24), high absolute fold-change (e.g. GABRA1) or DMR result (e.g. MNX1)." (PMID 37434245, 2023). "Notably, these cytotoxic effects elicited by N803 resulted in efficient lysis of cancer-stem cell-rich chordoma cell lines in vitro via mAbs targeting PD-L1 and the epidermal growth factor receptor (EGFR)." (PMID 37371081, 2023). "Another EGFR inhibitor, Afatinib, showed promising results against chordoma cells." (PMID 37111759, 2023).
chordoma (continued). "Despite the identification of numerous genes with dysregulated expression in vitro or in vivo in chordoma (e.g. brachyury, EGFR, Ezrin, MMP-9, c-MET, FHIT, etc.) conventional or targeted chemotherapeutic agents showed a partial response at best-case scenarios in clinical case-series." (PMID 36033338, 2022). "Gefitinib and afatinib, EGFR inhibitors, were also effective in chordoma patients." (PMID 36185236, 2022). "Notably, direct EGFR inhibitors have shown promise as anti-cancer agents in chordoma and are being clinically evaluated." (PMID 36059685, 2022). "In chordomas, the overexpression of EGFR has been widely reported." (PMID 36430263, 2022). "EGFR inhibitors were regarded as a potential therapy for chordoma." (PMID 36520826, 2022). "Additionally, the combination of cetuximab and gefitinib, both EGFR inhibitors, have demonstrated to be effective in the treatment of chordomas." (PMID 36258855, 2022). "Afatinib has been verified as a potential treatment for chordomas by targeting EGFR and TBXT." (PMID 36520826, 2022). "Dasatinib has shown modest efficacy in chondrosarcoma, whereas imatinib—and lapatinib when EGFR overexpression is detected—may be useful in advanced chordoma." (PMID 36430263, 2022). "Clival chordoma cell lines were more responsive to combined EGFR-MET inhibition." (PMID 34550531, 2021). "However, the combination of crizotinib with the EGFRi afatinib results in synergistic effects not only in chordoma cells resistant to EGFR inhibition for U-CH2, but also in chordoma cells that respond to EGFRis." (PMID 34550531, 2021). "Supported by these data, a European multicentre clinical trial involving a second-generation EGFR inhibitor (afatinib or Giotrif®, Boehringer Ingelheim, Ingelheim, Germany) is currently enrolling patients with advanced and metastasising chordoma (ClinicalTrials.gov Identifier: NCT03083678)." (PMID 34550531, 2021). "However, RAS-transformed cells lead to activation of downstream signalling driven by EGFR, a cell surface receptor highly involved in chordomas, mimicking upstream receptor tyrosine kinase (RTK) activation." (PMID 33579726, 2021). "Our previous study shows that phosphorylated EGFR plays important roles in chordomas progress." (PMID 34560882, 2021). "So far, except for EGFR, few cell surface antigens were known to be overexpressed in chordoma." (PMID 34868903, 2021). "Using in vitro cytotoxicity models, we demonstrated that anti-programmed death ligand 1 (anti–PD-L1; N-601) and anti-EGFR (cetuximab) antibodies enhanced lysis of chordoma cells by healthy donor and chordoma patient NK cells through antibody-dependent cellular cytotoxicity (ADCC)." (PMID 35765577, 2021). "EGFR is expressed in the cell membrane, and the expression rate of chordoma is 35% to 100%." (PMID 32011476, 2020). "Chordoma with serious dural penetration highly expressed EGF and AKT3 and show evidence of EGFR activation suggesting that RTK inhibitors may be useful for the treatment of dural invasion in chordoma." (PMID 32533822, 2020). "In addition to this preclinical data, some clinical evidence exists to support EGFR and its therapeutic agents as potential chordoma treatments." (PMID 32737414, 2020). "A body of such molecular, preclinical, and clinical evidence of interest to chordoma oncogenesis has begun to emerge for several kinases: Epidermal Growth Factor Receptor (EGFR), Cyclin-dependent kinase 4 (CDK4), Cyclin-dependent kinase 6 (CDK6) and the mammalian target of rapamycin (mTOR)." (PMID 32737414, 2020). "Nevertheless, accounts of partial treatment response of metastatic chordoma to combination cetuximab/gefitinib provide further evidence that drugs targeting the EGFR signaling pathway may benefit chordoma patients." (PMID 32533822, 2020).